PLB1 (phospholipase B1)
Description:
Calcium-independent membrane-associated phospholipase that catalyzes complete diacylation of phospholipids by hydrolyzing both sn-1 and sn-2 fatty acyl chains attached to the glycerol backbone (phospholipase B activity) (By similarity). Has dual phospholipase and lysophospholipase activities toward diacylphospholipids. Preferentially cleaves sn-2 ester bonds over sn-1 bonds. Acts as a lipase toward glycerolipid substrates (By similarity). Hydrolyzes fatty acyl chains of diacylglycerols with preference for the sn-2 position and of triacylglycerols with not positional selectivity (By similarity). May also hydrolyze long chain retinyl esters such as retinyl palmitate (By similarity). May contribute to digestion of dietary phospholipids, glycerolipids and retinoids, facilitating lipid absorption at the brush border (By similarity).
Synonyms: PLB/LIP; PLB; FLJ30866
Tractability: Antibody: its Gene Ontology location is reachable by antibodies, with high confidence; UniProt places it where antibodies can reach, with medium confidence; UniProt predicts a signal peptide or a membrane-spanning region.
Gene: Protein-coding gene on chromosome 2 (28,457,145 to 28,644,142, forward strand). Ensembl gene ENSG00000163803.
Subcellular location: Apical cell membrane
Pathways (Reactome):
Metabolism: Acyl chain remodelling of PC
Sensory Perception: Retinoid metabolism and transport
Gene Ontology:
Molecular function: phosphatidylcholine lysophospholipase activity; phospholipase A2 activity; retinyl-palmitate esterase activity; triacylglycerol lipase activity; diacylglycerol lipase activity; hydrolase activity, acting on ester bonds; lipase activity; monoacylglycerol lipase activity; phospholipase activity
Biological process: phosphatidylcholine acyl-chain remodeling; phospholipid metabolic process; retinoid metabolic process; diacylglycerol catabolic process; lipid metabolic process; phosphatidylcholine catabolic process; phosphatidylethanolamine catabolic process; phosphatidylglycerol catabolic process; retinol metabolic process; triglyceride catabolic process
Cellular component: apical plasma membrane; brush border membrane; plasma membrane
Genetic constraint (gnomAD): Loss-of-function variants: 220 observed, 220.86 expected, observed/expected ratio (o/e) 1, 90% interval 0.89 to 1.11. The upper end of that interval is the gene's LOEUF score, 1.11, which puts it in group 4 of 6, group 1 being the genes least tolerant of losing a copy. Missense variants: 1,781 observed, 1,807.6 expected, observed/expected ratio (o/e) 0.99, 90% interval 0.95 to 1.02. Synonymous variants: 733 observed, 686.66 expected, observed/expected ratio (o/e) 1.07, 90% interval 1 to 1.13.
Homologues: Orthologues: chimpanzee PLB1 (99% identical), macaque PLB1 (94% identical), dog PLB1 (79% identical), pig PLB1 (75% identical), guinea pig PLB1 (72% identical), rabbit PLB1 (72% identical), rat Plb1 (69% identical), mouse Plb1 (69% identical), tropical clawed frog plb1 (47% identical), zebrafish plb1 (30% identical), Drosophila melanogaster CG7365 (10% identical), Drosophila melanogaster CG11029 (10% identical), and 10 more.